DPP9 (dipeptidyl peptidase 9)
Diseases named in the same sentence as DPP9 in open-access papers (continued):
Sharing a sentence is not in itself a finding about the gene and the disease.
cancer (15 papers, 2013 to 2026). A tumor composed of atypical neoplastic, often pleomorphic cells that invade other tissues. "Dipeptidyl peptidase 9 (DPP9) is an amino-peptidase with roles in immunity, DNA-repair, cell signaling, memory and neonatal survival; its dysregulation is linked to cancer and immune-related disorders." (PMID 41636814, 2026). "DPP9 has crucial roles in inflammatory regulation, DNA repair, cellular homeostasis, and cellular proliferation, while its deregulation is linked to cancer and immunological disorders." (PMID 40293537, 2025). "This is the first set of analysis of human genomic databases to examine DPP9 exonic LoF variants and the of association of DPP9 expression with cancers." (PMID 33915844, 2021). "We have examined the associations between DPP9 mRNA expression and several potential prognostic factors, including gender, age, cancer stage and BMI." (PMID 33915844, 2021). "This study identifies DPP9 exonic LoF variants in human genomic databases and their associations with cancers." (PMID 33915844, 2021). "There were many more DPP8 than DPP9 LoF gene variants in TCGA, found in diverse types of cancer, mostly in UCEC and one in HCC." (PMID 33915844, 2021). "DPP9 was found to be very LoF-intolerant and its LoF exonic variants were mostly associated with cancers." (PMID 33915844, 2021). "Human genomic databases, including The Cancer Genome Atlas (TCGA), were interrogated to identify DPP9 LoF variants and associated cancers." (PMID 33915844, 2021). "DPP9 loss-of-function exonic variants were mostly associated with cancers." (PMID 33915844, 2021). "Notably, patients with DPP9 LoF variants were most commonly diagnosed with cancers." (PMID 33915844, 2021). "DPP9 can have different outcomes in different cancer cell lines, so these phenomena require further study." (PMID 40293537, 2025). "We next explored closely the association of DPP9 with clinical parameters relevant to HCC, including gender, age, BMI and cancer stages." (PMID 33915844, 2021). "DPP9 is ubiquitously expressed in tissues and has diverse roles in cell behaviors, immune regulation and cancer." (PMID 33915844, 2021). "Thus, further investigations are required for discovering and characterizing more DPP9 substrates, as well as investigations in cancer models for a deeper understanding of the different modes in which DPP9 affect cancer progression." (PMID 40293537, 2025). "For example, never-smokers displayed a greater proportion of hypomethylated differentially methylated regions (hypoDMRs) and a greater number of recurrently hypomethylated promoters, including those of ASPSCR1, TOP2A, DPP9, and USP39, all previously linked to cancer." (PMID 37742993, 2023). "Perhaps the role of DPP9 that is dominant differs in different cancer types and differs depending upon whether high or low DPP9 expression occurred in the tumor or was life-long." (PMID 33915844, 2021). "DPP8 and DPP9 have been assigned important roles in different physiological settings including roles in the immune system, in inflammation, in preadipocyte differentiation, and during cancer progression." (PMID 32815200, 2020). "Furthermore, DPP9 may also influence cancer progression via additional pathways." (PMID 40293537, 2025). "It remains to be established whether compounds that, in addition to DPP-IV, inhibit other DPP-IV-like proteases, such as FAP, DPP8, and DPP9, may offer advantages over the use of more selective DPP-IV inhibitors in patients with cancer." (PMID 35565202, 2022). "The specific substrate or pathophysiological significance on cancer of DPP-8 and DPP-9 are not elucidated yet, but some tumor-promoting effects of either DPP-8 or DPP-9 have been reported." (PMID 34063285, 2021).
tumor (13 papers, 2013 to 2025). "For example, in tumor cells Huh7 and HeLa, the localization of DPP9 was found to be associated with mitochondria and microtubules." (PMID 36172198, 2022). "Proteases may act as tumor suppressors as exemplified by DPP4 which is homologous to DPP9, both encode proteins that harbor the DPPIV-domain as well as hydrolase and peptidase conserved domains." (PMID 28893231, 2017). "However, rearrangements of DPP9, leading to decreased expression of its 3′ end, were identified in two cases and might possibly result in loss of tumor suppressor function." (PMID 28893231, 2017). "Concordantly, increased cell proliferation in vitro, and tumour size and mass in vivo, has been observed when DPP9 is silenced in an oral squamous cell carcinoma cell line." (PMID 40293537, 2025). "These hepatocyte-DPP9 depleted mice also exhibited lower blood glucose, body mass and adipose tissue mass, so improved energy metabolism is potentially involved in the tumour outcome." (PMID 40293537, 2025). "Nevertheless, 100% of lesions were DPP9-high, suggesting that DPP9 is potentially a candidate biomarker for neoplasm identification in this model, as well as indicating that tumours contain ample DPP9 for DPP9-targeted therapies." (PMID 34771657, 2021). "The DPP9 protein participates in cell signaling and has several tumor suppressing abilities such as inducing apoptosis, suppressing proliferation, and attenuating activation of the oncogene AKT (protein kinase B)." (PMID 28893231, 2017). "Moreover, Val-boroPro enhances activation of lymph node draining T cells via dendritic cells and T-cell tumour infiltration, hence promoting tumour regression, possibly by acting upon DPP9." (PMID 40293537, 2025). "Moreover, it appears that pyroptosis driven by DPP9 inhibition puts these tumours into a pro-inflammatory state, with increased Th1 cell activation and immune response." (PMID 40293537, 2025). "Therefore, the effect of DPP8 and DPP9 on tumor cell proliferation and apoptosis seems to be cell-type-specific." (PMID 37626841, 2023). "DPP9 affects the adhesive migration of tumor cells via colocalizing with cytoskeletal proteins." (PMID 36172198, 2022). "From our analyses, DPP9 (Dipeptidyl Peptidase 9), LRRC20 and TTBK2 expressions were the top three upregulated genes that may be associated with the homing of the migrated tumour cells in the bone." (PMID 35685372, 2022). "In addition, some studies have found that DPP9 is involved in the adhesion and migration of tumor cells." (PMID 36172198, 2022). "In tumor cells and fibroblasts, DPP9 may participate in cell adhesion and migration and locates adjacent to the edge of the plasma membrane." (PMID 36172198, 2022). "DPP9 may be selectively upregulated during carcinogenesis and might be a potential marker for precancerous lesions and tumours." (PMID 34771657, 2021). "Since Syk appears to act as a negative regulator of specific tumours, inhibition of DPP9 to stabilize Syk in these cells may reflect a future approach for tumour therapy." (PMID 27614019, 2016). "That outcome may indicate that tumour initiation, but not later growth, is retarded by DPP9 loss in hepatocytes." (PMID 40293537, 2025). "Inhibition of DPP4, DPP8, DPP9 and FAP by Val-boroPro has been shown to mediate regression in multiple tumour models, likely, at least in part, via the modulation of immune responses." (PMID 34771657, 2021). "DPP9 and its closest relative, DPP8, are primarily under study in cell biology, immunobiology and tumor biology." (PMID 24223149, 2013). "DPP9 can influence antigen processing, epidermal growth factor (EGF)-mediated signaling and tumor biology." (PMID 24223149, 2013). "Moreover, an adjuvant effect triggered by inhibition of DPP9 and DPP8 appears to be a mechanism by which the compound Val-boro-Pro mediates tumor regression." (PMID 24223149, 2013).
infection (8 papers, 2022 to 2025). The state of being infected such as from the introduction of a foreign agent such as serum, vaccine, antigenic substance or organism. "Alternative splicing of DPP9 also had high posterior probabilities of a shared single causal signal for critical illness (0.96), hospitalization (0.96), and reported infection (0.95)." (PMID 37794074, 2023). "Thus, it seems plausible that a biomolecule similarly inhibits DPP9 and triggers inflammasome activation during infection, but one has not yet been discovered." (PMID 39615677, 2025).
DPP9 also shares sentences with these, for which no sentence is quoted: idiopathic pulmonary fibrosis (4 papers); respiratory failure (4); pancreatic cancer (3); cervical cancer (2); diabetes (2); idiopathic interstitial pneumonia (2); respiratory disease (2); type 2 diabetes (2); acute respiratory distress syndrome (1); autoimmune disease (1); bacterial infection (1); bacterial pneumonia (1); chronic lymphocytic leukemia (1); chronic obstructive lung diseases (1); endothelial dysfunction (1); glioma (1); heart failure (1); IgA nephropathy (1); influenza (1); leukemia (1); liver fibrosis (1); lung (1); lymphoma (1); meningioma (1); nasopharyngitis (1); Pancytopenia (1); pulmonary hypertension (1); Reticulocytopenia (1); sarcoma (1); testicular cancer (1).
A further 3 diseases each share a sentence with DPP9 in 1 paper.